IL2 (interleukin 2)
Diseases named in the same sentence as IL2 in open-access papers (continued):
Sharing a sentence is not in itself a finding about the gene and the disease.
tumor (continued). "Pro-inflammatory cytokines including IL-2, IL-12, and IFN-γ promote anti-tumor immunity by enhancing T cell proliferation, Th1 differentiation, and CTL function." (PMID 40806379, 2025). "For example, TanCAR T-cells that target both HER2 and CD19 have demonstrated the capacity to destroy tumor cells expressing either antigen while releasing key effector molecules like IFN-γ and IL-2." (PMID 40940995, 2025). "The results were evident, with a doubling of NK cell counts, a substantial increase in cytokine levels such as IL-2, TNF-β, and IFN-γ, and a marked decrease in various tumor markers, including circulating tumor cells (CTC)." (PMID 40391220, 2025). "Bempegaldesleukin (NKTR-214) has been developed as a novel pegylated interleukin-2 (IL-2) cytokine prodrug that activates effector CD8+ T cells and NK cells within the tumor microenvironment." (PMID 40647561, 2025). "IFN-γ operates downstream of IL-12 and IL-2 signaling, playing a crucial role in macrophage activation, MHC upregulation, and anti-tumor effects." (PMID 40860882, 2025). "We also offer an overview of changes in the NK cell transcriptional program upon simultaneous exposure to IL-2 and TGF-β, a slightly more complex system more closely resembling in vivo pathophysiological situations, such as the tumor microenvironment." (PMID 40155684, 2025). "IL-2 can stimulate the growth of NKs, however, when Tregs and NKs are cocultured, Tregs can inhibit the proliferation of NKs by competing with IL-2, indicating that the affinity between Tregs and IL-2 may be dominant, which can weaken the immune ability and facilitate the escape of tumor cells." (PMID 40008144, 2025). "ELISA assays within the co-culture system demonstrated that Tregs competitively deplete IL-2 in conjunction with CD8+ T cells, thereby attenuating the immune activation of CD8+ T cells within the tumor microenvironment." (PMID 40698080, 2025). "Tumor cells that were infected with EphA2-TEA-VV induced the activation of T cells, as indicated by the release of IFN-γ and IL-2." (PMID 38464532, 2024). "CAR-T cells were shown to effectively kill tumor cells, and high levels of cytokine secretion such as IFN-γ, IL-2 and TNF-α were found." (PMID 38339374, 2024). "ICK and IL‐2‐Fc had comparable antitumor effects in both tumor models, although ICK had higher tumor uptake and slower blood clearance than an IL‐2‐Fc." (PMID 38317590, 2024). "In this context, we analysed the role of the IL-2 and CD95 pathways, essential molecules in activating the immune system and eliminating tumour cells." (PMID 39766250, 2024). "Platycodin D, a major component of Platycodon grandiflorum roots and a component of GJS, significantly inhibits tumor growth by increasing interferon-γ, TNF-α, IL-6, and IL-2 levels and improves immune function." (PMID 39273195, 2024). "CD4+ T cells can present tumor antigen epitopes; promote the activation of CD8+ T cells and the effector and memory functions of CTLs; and secrete IFN-γ, IL-2, and TNF-α to improve CTL activity and assist in killing tumor cells." (PMID 39408814, 2024). "Activated NKG2D/Dap10-12 T cells produced interleukin (IL)-2 and interferon (IFN)-γ and expanded and maintained cytotoxic activity when re-stimulated on tumor cell monolayers." (PMID 39566469, 2024). "When T cells are activated by corresponding tumour antigens, they express surface activation markers such as 41BB, CD69 and CD25 and produce effector molecules such as IL-2, TNF-α, IFN-γ, perforin and granzymes." (PMID 38727812, 2024). "The first immunotherapies to become FDA-approved were the anti-tumor cytokines interferon-alpha 2 (IFN-a2) and interleukin-2 (IL-2), molecules that stimulate T-cell proliferation." (PMID 39451258, 2024). "Some tumor cells express IL-2 receptors, and upon binding with IL-2, intracellular signaling pathways are activated, such as the PI3K/Akt pathway, which promotes tumor cell survival and proliferation." (PMID 39867885, 2024).
tumor (continued). "Compared to conventional CAR-T cells, CAR-ss-T cells produced higher levels of interferon-γ (IFN-γ), IL-2, tumor necrosis factor-α (TNF-α) and granzyme B (GZM) against MSLN-expressing HGC27 and MKN45 tumor cells." (PMID 38368374, 2024). "These IL-2 ICs with S4B6, MAB602, or JES6-5H4 exhibited strong antitumor activity in various murine tumor models." (PMID 39218982, 2024). "TCR-engineered CD8+ T cells secreted IL-2, IL-4, IL-6, and IL-10 when cocultured with KRASG12V tumor cell lines." (PMID 39287991, 2024). "Recombinant Newcastle disease virus strains expressing cytokines such as IL-2, IL-15, or TRAIL stimulate tumor-specific CTL responses, inducing CD4+ and CD8+ T cell proliferation, leading to tumor regression." (PMID 38731910, 2024). "Furthermore, the addition of PTA to this system further enhanced the effector functions, with Vγ9Vδ2 T cells killing approximately 80% of Raji cells in 1 h at the E/T ratio of 200, confirming that the PTA/IL-2-expanded Vγ9Vδ2 T cells could exhibit potent effector functions against tumor cells." (PMID 38426765, 2024). "Th1 cells are known for their role in the production of IFN‐γ, IL‐2 and TNF‐α, among other cytokines, making them the primary Th cell subset involved in the anti‐tumour immune response." (PMID 38898693, 2024). "Tumor-infiltrating lymphocyte (TIL) therapy has been restricted by intensive lymphodepletion and high-dose intravenous interleukin-2 (IL-2) administration." (PMID 38769543, 2024). "Consistent with ADAM17 KO mice, CAR-T cells with ADAM17 inhibition displayed increased CD122 expression in both tumor and draining LNs, as well as STAT5 phosphorylation after IL-2 stimulation ex vivo." (PMID 38918390, 2024). "This treatment also increased the infiltration of CD8+ T cells and macrophages, as well as the mRNA expression levels of IL-12, IFN-γ, IL-2, IL-10, TNF-α, and PD-L1 in the tumor microenvironment." (PMID 39367471, 2024). "In TNBC-bearing mice, tmTNF-α CAR-T therapy led to significant tumour regression, improved survival, and elevated serum IFN-γ and IL-2 levels." (PMID 39596267, 2024). "We found that the knockdown of DPP7 in tumor cells increased the level of IL-2 in the co-culture system, while overexpression of DPP7 decreased the level of IL-2 in the medium." (PMID 39247602, 2024). "These tumor cell lines were co‐cultured with FAP‐CAR‐T cells or CAR‐T cells targeting an irrelevant antigen (EphA3) for 48 h, and the level of IL‐2 in the culture supernatant was measured by ELISA." (PMID 38975278, 2024). "In contrast, a number of studies have shown that CD276 inhibits anti-tumor immunity, including suppression of CD4+ and CD8+ T cell activation and proliferation, and reduction of IL-2 and IFNγ production." (PMID 38637557, 2024). "As a result, synNotch–IL-2 CAR T cells promoted infiltration into the target tumor and improved the efficiency of cancer cell elimination and survival in mouse tumor models of pancreatic cancer and melanoma." (PMID 38491394, 2024). "In mice, the targeted delivery of IL2, TNF, and IL12 led to a potentiation of the cytokine payload as a result of increased density and activity of tumor resident T cells and NK cells, capable of neoplastic cell recognition." (PMID 38448543, 2024). "It has been observed that cytokines such as IL-2, IL-12, IL-15, IL-18, and TGF-β can modulate the anti-tumor immune response mediated by NK cells, offering new strategies and choices for immunotherapy by regulating the function and activity of NK cells." (PMID 39221244, 2024). "On the other hand, EVs derived from DCs inhibit tumor growth by activating IFN-γ producer CD8+ T cells, increasing IL-2 expression and inhibiting regulatory T cells." (PMID 39559560, 2024). "TIL-ACT included tumor collection, ex vivo TIL expansion, lymphodepletion with cyclophosphamide and fludarabine, TIL transfer, and in vivo TIL stimulation with interleukin 2 (125 000 IU/kg, 10 days)." (PMID 39801681, 2024).
tumor (continued). "Antibiotic treatment was shown to disrupt glycerophospholipid metabolism, which directly affected cytokine expression in the tumor microenvironment and reduced levels of IFN-γ and IL-2, critical to effective antitumor immunity." (PMID 39767682, 2024). "Notably, these reports of efficacy of i.t. modalities extend beyond OVs – where the cytokine may function together with other viral mechanisms of action – to include tumor-targeted immuno-cytokines and naked cytokine proteins, thus far primarily focusing on IL-2 and IFNα." (PMID 39252938, 2024). "The results showed that XLLXF combined with trastuzumab significantly increased the levels of IL-15, IL-2, TNF-α, and IFN-γ in the sera of tumor-bearing nude mice." (PMID 38379418, 2024). "In co-culture with tumor cells and monocytes, stCAR T cells exhibited anti-tumoral activity and potent release of CRS-related cytokines (IL-6, IFN-γ, TNF-α, GM-CSF, IL-2, IL-10)." (PMID 38514793, 2024). "By competing for intratumoral IL-2, Tregs prevented the activation of CD8+ tumor-infiltrating lymphocytes, drove thymocyte selection-associated high mobility group box protein (TOX) induction, and induced bona fide CD8+ T cell exhaustion." (PMID 38787791, 2024). "This process is facilitated by the production of various cytokines and chemokines, including TNF-α, IFN-γ, IL-2, IL-12, IL-21, IL-15, IL-18, CXCR3, and granulocyte-macrophage colony-stimulating factor (GM-CSF), which actively promote anti-tumor immunity." (PMID 38533507, 2024). "A tanapoxvirus (TPV) was engineered to express monocyte chemoattractant protein (CCL2) or IL-2 (TPV/D66R/mCCL2 and TPV/D66R/mIL-2) as a safer oncolytic virus with selectivity for tumor cells." (PMID 38803496, 2024). "MPE-Tem and MPE-Tcm secreted more IFNγ, TNFα, and IL-2 compared to paired MPE-TemRA and MPE-Tnaive, which were used to kill tumor cells." (PMID 39372862, 2024). "Morphine regulates immune factors (IL-2, IL-10, TGF-β, and PD-L1), thereby promoting tumor immune escape." (PMID 38361933, 2024). "Immune cytokines, including IL-2, interferon-alpha (IFN-α), and granulocyte-macrophage colony-stimulating factor (GM-CSF), modulate the tumor microenvironment and activate immune cells." (PMID 38594256, 2024). "We also found that B-ISG15 was enriched in the IL2 STAT5 signaling and IL6 JAK STAT3 signaling gene sets, and IL-6/JAK/STAT3 signaling drives tumor cell proliferation, survival, invasion, and metastasis while inhibiting the antitumor immune response." (PMID 38216927, 2024). "This was accompanied by a decrease in the induction and proportion of tumor-infiltrating multifunctional CD8+ T cells expressing IFN-γ, TNF-α, or IL-2." (PMID 38886748, 2024). "TanCARs’ cytotoxic-killing effect led to a higher production of cytokines such as IL-2 and IFN-γ, particularly against tumour cells showing both antigens compared to tumour cells that only expressed a single one." (PMID 39596267, 2024). "Th1 cells are generally considered as anti-tumor immune cells that inhibit tumor growth and activate tumor-specific immune mechanisms by producing IFN-γ, TNF-α, and IL-2." (PMID 38293522, 2024). "In summary, our findings suggest that cytokines, such as IL‐2 used here, can stimulate the non‐transduced fraction of a CAR‐T cell product to also mediate tumor cell killing." (PMID 38975278, 2024). "It triggered apoptosis and reduced further damage to tumor cells while enhancing the levels of cytokines like TNF-α, IL-2, and immune cells, including macrophages, lymphocytes, and NK cells." (PMID 38794206, 2024). "Ongoing trials with bempegaldesleukin (NKTR-214; pegylated recombinant IL2) plus anti-PD1 (NCT02983045) continue to demonstrate well-tolerated and anti-tumor efficacy in metastatic urothelial carcinoma." (PMID 38785789, 2024). "CAR-T cells, regardless of having an additional co-stimulatory domain, proliferated in the presence of EphA2+ tumor cells, exhibited cytolytic activity and produced cytokines: IFN-γ and IL-2." (PMID 38339374, 2024).
tumor (continued). "In turn, intratumoral infiltrating lymphocytes secrete IL-2 to activate tumor STAT5A signaling, which further synergizes with TET2 to epigenetically upregulate tumor cGAS, indicating a positive feedback loop." (PMID 38177099, 2024). "The selected pure lymphocyte cultures will then be co-cultured with lymphocytes and tumor cells in the presence of irradiated feeder lymphocytes (an antibody targeting ε subunits within human CD3) and IL-2 to rapidly expand for 5 to 6 weeks." (PMID 39238638, 2024). "It is noteworthy that IL2/IL12 plays a pivotal role in the survival and activation of T lymphocytes, serving as a crucial component in anti-tumor responses." (PMID 38881859, 2024). "IL-2 depletion enriched an exhaustion-prone subset of CD8+ TILs (cluster 11), characterized by CD44hiTcf1–TOX+Tim3+Lag3+PD-1+TIGIT+CD8+ in MC38 tumor–bearing KO mice." (PMID 38787791, 2024). "Once activated, CD8 T lymphocytes release IFN-γ, IL-2, and TNF-α, crucial cytokines for the differentiation of T cells into CTLs, which are responsible for the direct destruction of tumor cells." (PMID 39682686, 2024). "Following the co-culture, we measured the levels of Tumor Necrosis Factor-α (TNFα), Interferon-γ (IFNγ) and Interleukin-2 (IL2), important for T-cell anti-tumor activity and proliferation." (PMID 39512355, 2024). "For instance, by combining high-affinity CD16 V158 FcγRIIIa receptor and IL-2 expression in engineered NK92 cells, enhanced lysis of tumor cells was observed with diverse combinations of monoclonal antibodies and target cells." (PMID 38443448, 2024). "Only with simultaneous activation of the Vδ2 T cell TCR, which recognizes phosphoantigens on stressed, infected or tumor cells, did CAR-DAP10 signaling mount a full response with release of IFN-γ, TNF-α, IL-2, IL-4, GzmB and cytotoxicity against tumor cells." (PMID 39061247, 2024). "Because it cannot produce IL-2, Tregs compete with CD8+ T cells to deplete IL-2 in the TME, thus preventing the anti-tumor immunity of CD8+ T cells." (PMID 39372416, 2024). "Other than immune-modulating cytokines such as IL-10, IL-17, IL-23, and TGF-β (assisting tumor growth), IFN-γ, TNF-α, GM-CSF, IL-2, IL-6, IL-17, and IL-1 stimulate immune surveillance and prevent tum development." (PMID 38951583, 2024). "Effector CD8 T cells in the TME produce IL-2, IL-12, and IFN-γ to enhance the cytotoxic potential of CD8 TILs to target the tumor cells." (PMID 39238638, 2024). "For instance, CD4+ helper T cells sustain the leukocytic anti-tumor functions through cytokine secretion (IFN-γ, TNF, and IL-2) while modifying the antigen presentation of DCs and B cells via direct CD40/CD40L interactions." (PMID 38673829, 2024). "In pre-REP, TILs resident in tumour fragments receive—in addition to IL-2—signals through the T cell receptor (TCR) and possibly through co-stimulatory CD28 from adjacent tumour-resident antigen-presenting cells." (PMID 38658764, 2024). "The tumor growth curves for each therapy showed equivalent efficacy between ICK and IL‐2‐Fc treatments." (PMID 38317590, 2024). "The dysregulation of this pathway promotes tumor cell resistance to Fas-mediated apoptosis and IL-2 signaling-mediated activation of the JAK/STAT, NF-kB and MAPK pathways, leading to tumor cell proliferation and survival." (PMID 38610985, 2024). "When comparing these results to the therapeutic studies above, it appears that although more ICK goes to the tumor postinjection, both ICK and IL‐2‐Fc remain equally efficacious supported by strong immune organ uptake." (PMID 38317590, 2024). "Upon recognizing tumor antigens, CAR T cells secrete pro-inflammatory cytokines, such as IL-2, IFN-γ, and TNF-α, to regulate cell growth, activation, and differentiation." (PMID 38683232, 2024). "Apoptosis of tumor cells, the ratio of CD8+/CD4+ in CD3+ cells, CD80+CD86 in DD11c+ cells, and IFN-γ+ in CD3+ all were significantly higher than challenge with IL-2 or the microorganism alone." (PMID 38585738, 2024).
tumor (continued). "The authors examined that EGFR806-CAR-T cells with short spacers in the extracellular domain induced the strongest production of effector cytokines IL-2, IFN-γ and TNF-α after tumor recognition." (PMID 38339374, 2024). "To further understand the pro-inflammatory impact of GzB-IL18, we co-cultured pCAR-H/T T cells and their armored derivatives with MDA-MB-468 tumor cells or anti-CD3+CD28 beads and measured tumor necrosis factor (TNF)-⍺ and IL2 in derived supernatants." (PMID 38745414, 2024). "Collectively, targeting Treg-specific gp96 not only prevents Treg infiltration into the TME but also hampers their activation due to suboptimal IL-2/p-STAT5 signaling, contributing to heightened antitumor immunity and superior tumor control." (PMID 38787791, 2024). "In a study using irradiated EBV-LCL feeder cells with IL-2, the increased expression of CXCR3 by NK cells led to improved homing and tumor-killing activity against CXCL10-transfected melanoma xenograft mice." (PMID 39339180, 2024). "Consistent with the cytotoxic potential of UniCAR T-cells obtained, the secretion of Interferon gamma (IFNγ), Interleukin 2 (IL-2) and Tumor Necrosis Factor alpha (TNFα) increase in a TM dose-dependent manner in both FAP+ tumor models and for all TMs." (PMID 39000348, 2024). "However, when exogenous IL-15 engaged tumor cells, a complex containing the IL-15Rα, IL-2/IL-15Rβ, and IL-2Rγ chains was formed, indicating that the differential actions of intracellular and extracellular IL-15 on tumor cells might be caused by their distinctive modes of IL-15 receptor engagement." (PMID 38637902, 2024). "The variables included were ECOG, tumor stage, the indication for treatment, the type of ICI, the best response, LDH, IL-2 and IL-15." (PMID 39199571, 2024). "In this work, we generated a novel cellular model of TITRs by culturing peripheral blood mononuclear cell-derived regulatory T cells in medium containing tumor cell-conditioned medium, CD3/CD28 activator, interleukin-2 and 1α,25-dihydroxyvitamin D3." (PMID 38231448, 2024). "MHY1485 suppresses tumor growth in vivo under co-treatment with X-rays and increases INF-γ, tumor necrosis factor, interleukin-2 and interleukin-12 levels in the spleen as well as the presence of CD8+ cells in the tumor." (PMID 38330507, 2024). "These causes include 1) Direct tumor influence: Tumor cells produce cytokines like IL-1, IL-2, IL-6, and TNF-α, promoting tumor growth, disrupting normal cellular metabolism, and compromising bodily functions." (PMID 39872045, 2024). "PEGylated IL-2 (NKTR-214) offers a promising alternative, showing improved persistence and superior anti-tumor responses in combination with immunotherapies." (PMID 38891056, 2024). "The 16-biomarker panels were divided into three categories of inflammatory markers (SAA, CRP, NLR, PLR, and LDH), TH1/TH2 cytokines (IL-2, IL-4, IL-5, IL-6, IL-8, IL-10, IFNγ, TNF, and GM-CSF), and HCC tumor markers (AFP and PIVKA-II)." (PMID 38409200, 2024). "The activated CD44hiCD62lo CD8+ TIL population was slightly decreased by IL-2 and S4B6-1 administration, consistent with progressive tumor growth." (PMID 38787791, 2024). "These IL-2 muteins were more effective than wild-type IL-2 (IL-2wt) at stimulating CD8 + T cells and NK cells and inducing antitumor activity in preclinical tumor studies." (PMID 39595576, 2024). "NK cells are also an important source of cytokines in vivo, which can induce tumor eradication by secreting distinct cytokines (such as TNF-α, IFN-γ, IL-2, etc.)." (PMID 39065636, 2024). "In line with the manifestation of symptoms, the amounts of IL-2, TNF-α, and IFN-γ in the tumor-free stCAR T-cell group were higher than in the tumor-engrafted mice and came close to those observed in the presence of monocytes." (PMID 38514793, 2024).